CEACAM1 (CEA cell adhesion molecule 1)
Diseases named in the same sentence as CEACAM1 in open-access papers (continued):
Sharing a sentence is not in itself a finding about the gene and the disease.
cancer (continued). "Correlation of CEACAM1 expression with cancer stage and patient survival." (PMID 38077351, 2023). "As we did not observe TIM-3 expression on leukemic cell lines, we hypothesize that high TIM-3 levels on T cells (or other immune cells) in cancer might correlate with CEACAM1 expression on target or T cells." (PMID 35464394, 2022). "Moreover, we analyzed the correlation between TIM-3+ TILs infiltration and cancer tissue expressed CEACAM1." (PMID 34368221, 2021). "Number of cancer tissues analyzed for CEACAM1 expression in HNSCC." (PMID 34368221, 2021). "However, CEACAM1 is expressed not only on immune cells, but also on certain endothelial cells and epithelial cells, including cancer cells." (PMID 34336716, 2021). "Similarly, high expression for CEACAM1 in cancer tissue was suggested to have an unfavorable influence on OS and DFS (POS < 0.001, PDFS < 0.001)." (PMID 34368221, 2021). "Positive CEACAM1 expression was mainly observed in the membrane and cytoplasm of carcinoma cells." (PMID 34368221, 2021). "Although increased tissue expression of CEACAM-1 has been reported in human cancers, our findings of decreased expression may further explain earlier reports of a dual role of CEACAM-1 in BC." (PMID 33238953, 2020). "Moreover, in the results of miR-581 target genes, TNFSF10, HMGA2, CEACAM1, and mTOR have been reported to be involved in proliferation and apoptosis in a number of cancers." (PMID 32899503, 2020). "Abnormal splicing of ER, HER2, CEACAM1, and SRSF1 has been reported to contribute to breast tumorigenesis and prognosis, which could be an underlying target for cancer treatment." (PMID 32079071, 2020). "Whether CEACAM1 is a suppressor or promoter for malignant phenotype of cancer cells still remains controversial." (PMID 31481751, 2019). "A most recent study suggested that CEACAM1 overexpression significantly suppressed cancer cell proliferation, induced cancer cell apoptosis, and inhibited cancer cell invasion and migration possibly through activation of caspase-3 and downregulation of MMP-2 and MMP-947." (PMID 31358815, 2019). "Consequently multiple preclinical studies, but also clinical data in patients suffering from different cancer diseases, point to the significance of CEACAM1 as a novel therapeutic target." (PMID 30871206, 2019). "In this review, we discuss mechanisms of NKG2D-ligand regulation, with a focus on newly discovered mechanisms that promote NKG2D-ligand expression on epithelial cells, including ER stress, and mechanisms that suppress NKG2D-ligand-mediated killing of cancer cells, namely by co-expression of CEACAM1." (PMID 29973929, 2018). "The emerging picture of CEACAM1 in the context of cancer and the immune system is very complex." (PMID 30406153, 2018). "Isoform expression of CEACAM1 in tumoral tissue is particularly dynamic showing considerable downregulation within the epithelia in the early phases of many solid cancers such as prostate, colon, breast, and liver carcinomas." (PMID 30406153, 2018). "In survival analysis, we could show a significantly longer survival in carcinomas with high CEACAM1 mRNA levels (p = 0.008)." (PMID 30050594, 2018). "Pre-clinical studies targeting TIM-3 and CEACAM1 as cancer immunotherapy targets are promising." (PMID 29211042, 2017). "We are the first to report the utility of CEACAM1 as a serum diagnostic biomarker for OS and soluble serum CEACAM1 from OS patients was found to discriminate cancer from non-cancerous lesions." (PMID 27074014, 2016). "Combining CEACAM1 with other biomarkers for cancer has also offered promising results." (PMID 27074014, 2016). "In cancer tissues, CEACAM1 expression has obvious heterogeneity." (PMID 24587171, 2014). "However, investigations of transformed mammary epithelial cells (MCF7 cells) grown in a 3D-matrigel environment have suggested that CEACAM1-4S can induce lumen formation in these carcinoma cells resulting in acinar-like structures." (PMID 24735478, 2014).
cancer (continued). "In contrast, MCF7/CEACAM1 xenografts were organized and differentiated into a striated epithelium-like structure with abundant extra cellular matrix between the cells, resembling moderately differentiated carcinoma." (PMID 22332010, 2011). "The predominance of the CEACAM1-3A splice variant in cancer tissues was confirmed by conventional PCR (data not shown) and quantified by real-time PCR in 23 cases." (PMID 20525254, 2010). "Nevertheless, CEACAM1 has recently received considerable interest as a cancer antigen target." (PMID 16504122, 2006). "Interestingly, IRF1 and a variant of heterogeneous nuclear ribonucleoprotein L (Lv1) coordinately regulate CEACAM1 transcription, alternative splicing, and translation, and may significantly contribute to CEACAM1 silencing in cancer." (PMID 40002189, 2025). "Besides CRC, several studies indicate a potential role of CEACAM1 in multiple cancer entities." (PMID 38077351, 2023). "Thus, antibodies intended to block CEACAM1 signaling in cancer cells probably may induce the opposite effect depending on antibody design." (PMID 38077351, 2023). "Thus, the expression of CEACAM1 promotes the escape of cancers from immune surveillance." (PMID 37108808, 2023). "Genes containing AS events associated with overall survival are known components of cancer-related pathways, including regulation of transcription (E2F4, ZNF730, GPBP1, POLR2J, SP2, and CIART), cell cycle (E2F4 and GTSE1), or cell-cell adhesion (CEACAM1, MMP14, EPS8L2, AP3D1, AFDN, and PAK4)." (PMID 35044822, 2022). "Whether CEACAM1 is a good or bad molecule for cancer, however, remains controversial." (PMID 31481751, 2019). "However, CEACAM1 behaves as an oncogene in aggressive cancers." (PMID 29262644, 2017). "However, CEACAM1 expression correlative studies for cancer patients are controversial." (PMID 27074014, 2016). "Similarly, IIB stage patients had higher CEACAM1 than those with IIA stage cancers (P < 0.05)." (PMID 27074014, 2016). "Particularly, cumulative evidence from preclinical and clinical data together revealed a more complex influence, in particular for CEACAM1, CEACAM5, and CEACAM6 on cancer and CSCs." (PMID 41233805, 2025). "Members of this family, including human CEACAM1, CEA, and CEACAM6, are found on various epithelial cell types and derived carcinomas." (PMID 41373727, 2025). "The results of in vitro experiments indicated that CEACAM1 not only induced apoptosis of BLBC cells, but also inhibited the invasive and metastatic ability of cancer cells." (PMID 39513107, 2024). "Among these cell type markers of cell clusters, cancer cell cluster specifically expressed keratin 19 (KRT19) and CEA cell adhesion molecule 1 (CEACAM1), and TAM cluster expressed CD68, CD163, and complement C1q C chain (C1QC)." (PMID 38302412, 2024). "CEACAM1 can interact with various receptors, and we identified one possible interaction between tuft cell and immune cells, CEACAM1-HAVCR2 in PRT and human cancers." (PMID 37386128, 2023). "For example, sialic acid-binding immunoglobulin-like lectins (SIGLECs) and carcinoembryonic antigen-related cell adhesion molecule 1 (CEACAM1) are expressed by activated NK cells and their blockade enhances NK cell cytotoxicity against cancer cells." (PMID 37313600, 2023). "Our findings showed that MLKL was positively correlated with the expression of immune checkpoints such as PD1, PD-L1, PD-L2, and CTLA4 in most cancer types, except for ICOSLG, CD200, CEACAM1, HHLA2, and VTCN1 in BUC." (PMID 37000317, 2023). "For instance, a carcinoembryonic antigen-related cell adhesion molecule 1 (CEACAM-1) inhibits NK cytolysis in trophoblasts while it increases angiogenesis and metastasis in cancers." (PMID 36834865, 2023). "Depending on the cell type, CEACAM1, CEACAM5, and CEACAM6 play pivotal roles in particular aspects of cancer biology and immunology." (PMID 36741860, 2023). "Furthermore, we discuss potential CEACAM1-based mechanisms that may affect cancer biology." (PMID 38077351, 2023).
cancer (continued). "CEACAM1 is a transmembrane glycoprotein belonging to the carcinoembryonic antigen (CEA) family of proteins, which are known to play functional roles in cancer progression and neutrophil activation." (PMID 35267667, 2022). "NEO-201 has different mechanisms of action to kill target cancer cells, including ADCC, CDC and the blockade of the CEACAM5/CEACAM1 immune checkpoint inhibitory pathway." (PMID 36291783, 2022). "The published data on the relationship between the expression of several ICs—PD-L1, B7-H3, B7-H4, IDO1, Gal-3 and -9, CEACAM1, CD155, Siglec-15, and the ADAM17 immune response modulator—with the prognosis of cancer tumors, including GC, are analyzed." (PMID 34943606, 2021). "We reviewed data on the relationship between PD-L1, B7-H3, B7-H4, IDO1, Galectin-3 and -9, CEACAM1, CD155, Siglec-15 and ADAM17 expression with cancer development in complex with the results of clinical trials on their inhibition." (PMID 34943606, 2021). "Cancer cells investigated in our study—GBM43 and U87MG—express TIM-3 ligands, including galectin-9 and CEACAM-1, with both dominating in percentage on GBM43 cells and in MFI on U87MG cells." (PMID 32858904, 2020). "We measured expression of the receptors PD-1, CEACAM-1, LAG-3, CD158b, NKG2A and TIM-3 on activated human peripheral blood-derived NK cells prior to and after exposure to cancer targets." (PMID 32858904, 2020). "By western blotting we found that mAb 6G5j detected endogenously expressed CEACAM1, CEACAM5 and CEACAM6 in lysates of epithelial cell lines derived from gastric (MKN45) and colon (HT29, Caco-2) cancer cell lines." (PMID 32064046, 2020). "Unfortunately, the inhibition of pro-inflammatory actions caused by pathogens binding to CEACAM1 may have severe side effects, like triggering acute exacerbation of chronic obstructive pulmonary disease (AECOPD) and maybe even support the immune escape of cancer cells." (PMID 30871206, 2019). "CEACAM1, a member of the CEA family of Ig like transmembrane glycoproteins, is involved in the negative regulation of NKG2D-ligands in cancer." (PMID 29973929, 2018). "The importance of understanding the role of CEACAM1 in cell transformation stands not only in this adhesion molecule's value as a prognostic factor but also in its promising premise as a potential new molecular target that could be exploited as a specific cancer therapy." (PMID 30406153, 2018). "Moreover, whether KRAS status or mutations of other cancer driver genes in CRC patients (TCGA database) might have led to lack of CEACAM5 interaction with the other studied genes (CEACAM1, CEACAM6 and EPHA2) will need further investigation." (PMID 29262644, 2017). "Gain of 19q would result in increased copy number of several well known genes with involvement in cancer, such as BAX, CEACAM1, AKT2 and BCL2L12." (PMID 24144331, 2013). "However, our results revealed that overexpression of CEACAM1-3L and 4L not only induced apoptosis and inhibited the viability of BLBC cells, but also inhibited the invasive and metastatic potential of cancer cells." (PMID 39513107, 2024). "The CEACAM1-specific antibody CM24, developed by cCAM Biotherapeutics Ltd., has shown efficacy against different types of cancer cells in vitro and in in vivo models of cancer." (PMID 38077351, 2023). "In addition to ADCC, NEO-201 has different mechanisms of action to kill cancer cells expressing its target antigen, including CDC and the blockade of the CEACAM5/CEACAM1 immune checkpoint inhibitory pathway." (PMID 36991390, 2023). "In this review, we explore current knowledge surrounding CEACAM1, CEACAM5, and CEACAM6, highlight their pathological significance in the areas of cancer biology, immunology, and inflammatory disease, and describe the utility of murine models in exploring questions related to these proteins." (PMID 36741860, 2023).
cancer (continued). "Although several mAbs against CEACAM-5 have been found to be effective in diagnosis and therapy of several types of cancers, they failed to interfere with the CEACAM-1-CEACAM-5 interaction." (PMID 35804808, 2022). "The best performing model for discrimination between benign tumors and borderline tumors + cancer was a 6-biomarker combination (HE4, CA125, ITGAV, CXCL1, CEACAM1, IL-10RB) and age (AUC 0.868, sensitivity 0.86 and specificity 0.82, p = 0.016 for comparison with the reference model)." (PMID 33075095, 2020). "CEACAM1 stained lumen surface for adenocarcinoma that performed lumen, whereas CEACAM1 stained cancer cell membrane for adenocarcinoma that does not lumen formation." (PMID 31481751, 2019). "We also found IFN-γ induced the overproduction of IL-6 and IL-8 through CEACAM1, which may take part in the pathogenesis of AECOPD or the transition from inflammation to cancer." (PMID 31072323, 2019). "In the case of CEACAM1, no significance was found in either expression or prognosis between normal and cancer tissues." (PMID 31847101, 2019). "The knockdown of CEACAM1 by RNAi experiment resulted in the growth advantage of the corresponding cancer cells with no or low CEACAM1 expression." (PMID 31358815, 2019). "CEACAM1 expression in peritumoral tissues was negative or weak, whereas its expression was upregulated in cancer tissues compared with peritumoral tissues (P = 0.003)." (PMID 24587171, 2014). "Survival analysis revealed that overexpression of CEACAM1 was correlated with shorter cancer-related survival, but was not an independent prognostic factor for TSCC patients." (PMID 24587171, 2014). "However, the involvement of CEACAM1 in NSCLC and other cancers is complex, and further studies are required." (PMID 23885995, 2013). "Interestingly, some overlap exists with autoantibody responses in other cancers, such as MAGEA4 and CEACAM-1, which may reflect shared mechanisms in tumorigenesis." (PMID 39949781, 2025). "Therefore, CEACAM1 may contribute to the OS of BLBC patients by inhibiting the proliferation and metastasis of cancer cells." (PMID 39513107, 2024). "However, the hitherto results do not prove the inefficacy of targeting CEACAM1 in anti-cancer therapy." (PMID 38077351, 2023). "KEGG pathway analysis further highlighted the role of S6K1 in cancer progression, in which the depletion of S6K1 could re-express a group of tumor suppressor genes including RASSF5, RASSF6, STAT1, CEACAM1, BNIP3L and SOCS2." (PMID 32201535, 2020). "It is speculated that if the cancer cells are without CEACAM1 expression, enhanced CEACAM1 expression provokes less malignant phenotype of cancer including lumen formation." (PMID 31481751, 2019). "Our results suggested that CEACAM1-4S and CEACAM1-3S were more involved in IFN-γ-induced epithelial cell proliferation and migration, and might be the promoters to bridge between chronic inflammations and cancer." (PMID 31072323, 2019). "However, from those clinical studies at present it cannot be excluded that CEACAM1 upregulation might be a side effect rather than a driver of cancer progression and metastasis." (PMID 38077351, 2023). "Increasing the expressions of either CEACAM1 or CEACAM5, the ligand for NK CEACAM1, did not affect the killings against cancer cells by CD56+CD16+ NK cells, since these cells do not express CEACAM1." (PMID 21731662, 2011). "CEACAM1, like TGF-β, plays dual role in immune modulation and cancer, has been shown to interact with TGF-β members, is important for activation of CD8+ T cells, and the absence of CEACAM1 on virus-specific CD8+ T cells limits the antiviral CD8+ T-cell response." (PMID 40311681, 2025). "Stratified survival analysis showed that high CEACAM1 protein expression was prognostic in node-negative tumors (p = 0.045 and p = 0.0002 for DFS and OAS) but lost prognostic significance in node-positive carcinomas." (PMID 30050594, 2018).
infection (53 papers, 2009 to 2026). The state of being infected such as from the introduction of a foreign agent such as serum, vaccine, antigenic substance or organism. "There have also been residues reported in CEACAM1 that are crucial for determining the risk of infection by receptor-binding pathogens and preventing the killing activity of NK cells." (PMID 34447411, 2021). "In fact, pathogenic avian influenza virus (H5N1) infection of the lung epithelium stimulates the expression of CEACAM-1, which further induced production of pro-inflammatory chemokines." (PMID 33321840, 2020). "During infection, in vivo selection for phase variants expressing CEACAM1-specific Opa proteins occurs, allowing mucosal attachment and entry into the subepithelial space." (PMID 23935487, 2013). "We, therefore, used our CEACAM1-humanized mouse model in combination with deficiencies in C3 (C3−/-), C5 (C5−/-), C3aR1 (C3ar1-/-) C5aR1 (C5ar1−/-) or C5aR2 (C5ar2−/-) to monitor Nme nasal colonization following intranasal infection with 105 CFU." (PMID 31274379, 2019). "Post-infection, the Ceacam1-Ceacam1 signaling between GC cells and other epithelial cells was significantly weakened." (PMID 40786607, 2025). "To illustrate the performance of the COCONUT normalization, we visualized the log2 expression values of commonly used house-keeping genes (ATP6V1B1, and GAPDH) and genes known to be modulated by infection (CEACAM1 and DYSF) as previously shown." (PMID 38817614, 2024). "In activated CD4+ T cells expressing high levels of CEACAM1, IFNγ secretion is inhibited during infection with wild-type H. pylori in a HopQ-dependent manner." (PMID 36891299, 2023). "MHV-1 binds carcinoembryonic antigen-related cell adhesion molecule (CEACAM)-1, also known as CD66a, for viral entry and infection." (PMID 38259435, 2023). "In AGS cells infected with the ΔvirD4 isogenic strain, the level of CEACAM1 expression was stable and constitutive during 7 h infection." (PMID 35269634, 2022). "The results of the experiment revealed a slight increase in the level of human CEACAM1 expression upon infection with the ΔcagA strain." (PMID 35269634, 2022). "Reduced CEACAM1 expression was also detected within 1 h after infection and the magnitude of CEACAM1 reduction was correlated with elevated levels of CagA tyrosine phosphorylation in a time-dependent manner." (PMID 35269634, 2022). "It was observed that the expression level of CEACAM1 decreased at 7 h as observed previously, which was restored by 24 h of infection, suggesting that the expression of CEACAM1 oscillates throughout the infection period." (PMID 35269634, 2022). "The CEACAM-1-dependent pathway initially leads to IL-8 secretion via Erk1/2 and NF-κB signaling; IL-8 levels drop dramatically after 24 h of infection, possibly due to an A. baumannii-dependent effect on the CEACAM-1 intracellular domain." (PMID 33804894, 2021). "Following TMEV‐infection, CEACAM1 was additionally expressed in infiltrating mononuclear cells in the brain of B6 mice (Figure 5B5)." (PMID 34231271, 2021). "AIEC-HM605 infection induces the highest expression of CEACAM1, -3, -5, and -7 2 h post-infection (T2), with a reduction in CEACAM1, -5, -7 over time." (PMID 34394073, 2021). "Another gene that showed a significantly enhanced expression in B6 mice compared with SJL mice following TMEV infection was Ceacam1." (PMID 34231271, 2021). "We therefore studied the influence of the human CEACAM1 receptor in human CEACAM1-transgenic mice on the C. albicans colonization and infection utilizing a colonization/dissemination and a systemic infection mouse model." (PMID 31849868, 2019). "Nevertheless, Ceacam1–/– mice were able to control infection with 200 PFU of LCMV-WE at day 8 after infection." (PMID 29967450, 2018).